HMGB1 (high mobility group box 1)
Diseases named in the same sentence as HMGB1 in open-access papers (continued):
Sharing a sentence is not in itself a finding about the gene and the disease.
tumor (continued). "This may be due to HMGB1 passive release by dead tumor cells after treatment with EP." (PMID 30988279, 2019). "Interestingly, similar to other ICD inducers, PERK was necessary for P2Et induced elevation of Ecto-CRT and ATP release, but interestingly PERK also was necessary for HMGB1 release indicating the need for further research into the pathways involved in P2Et-induced tumor ICD." (PMID 31531232, 2019). "In the subgroup analysis by the type of malignancies, no obvious differences in tumor risks could be found in HMGB1 rs1045411 polymorphism amongst any cancer type except for BC." (PMID 30049847, 2018). "Furthermore, the expression of HMGB1 in tumor and normal margins was evaluated by means of IHC." (PMID 30245980, 2018). "Finally, autophagy also represents the mechanism that may limit tumorigenesis by restraining tumor necrosis and chronic inflammation, which are mediated by the release of proinflammatory high-mobility group box protein 1 (HMGB1)." (PMID 29783720, 2018). "However, whether HMGB1 expressed on tumor-derived exosomes can induce protumorigenic Breg production is not well known." (PMID 30526680, 2018). "Intriguingly, HMGB1 may also function as a tumor suppressor." (PMID 30049847, 2018). "Furthermore, dying-cell-derived HMGB1 activates the TLR2/PI3K/Akt pathways and induces the EMT program, which are important signaling events underlying radiotherapy-driven acceleration of tumor metastasis." (PMID 29615080, 2018). "HMGB1 could be a novel tumor promoter with therapeutic and prognostic relevance in cancers." (PMID 29844348, 2018). "Moreover, TLR pathway proteins such as TLR4, SARM1, and HMGB1 may play additional roles related to tumor development." (PMID 29472602, 2018). "Hence, HMGB-1 has been proposed as a target for tumor therapy." (PMID 29112161, 2017). "DAMPs, such as heat-shock proteins (HSPs), uric acid, high-mobility group box protein 1 (HMGB1), S100 proteins, DNA, RNA and ATP, has been revealed involving lots of pathological process, like I/R injury, atherosclerotic plaque formation, persistent pain and tumor growth." (PMID 28881795, 2017). "And even exogenous HMGB1 couldn't recover the delayed tumor growth by Gr-1 antibody." (PMID 28968989, 2017). "However, the mechanisms linking HMGB1 with tumor immune escape are unclear." (PMID 28968989, 2017). "HMGB1 could potentially regulate the amplification and involvement of MDSCs in tumor immune escape." (PMID 28968989, 2017). "Therefore, the tumour inhibition effect of sorafenib was better in the sh-HMGB1 group." (PMID 29246127, 2017). "In addition, NIR-PIT treated tumor cells demonstrated rapid releases of HMGB1 and ATP." (PMID 28060726, 2017). "HMGB1 may play a role in the bioenergetic output of the tumour." (PMID 29254158, 2017). "Based on our results in established MM tumor models, we speculated that EP might also have an inhibitory effect in asbestos-induced transformation of normal mesothelial cells due to the important roles of HMGB1 in asbestos carcinogenesis." (PMID 28186988, 2017). "However, the relationship between HMGB1 and MDSCs in tumor immune escape is studied rarely." (PMID 28968989, 2017). "However, the overall effects of HMGB1 on tumor growth are complex since, as detailed below, HMGB1 contributes to stimulating neoplastic cell growth and metastasis through different mechanisms, some of which are also involved in the enhancement of antitumor immunity." (PMID 26925422, 2016). "Additionally, staining of cytoplasmic HMGB1 was observed in a few tumor cells (arrows)." (PMID 27363018, 2016). "However, the mechanism of HMGB1 in tumorigenesis and tumor progression is partially understood." (PMID 26499944, 2016). "Indeed, HMGB1 could initially play a crucial role in amplifying the NK cell recruitment to the site of NK:tumor cell interaction; next, it could improve the patrolling capability of NK cells that have reached the tumor by enhancing their motility." (PMID 27294158, 2016).
tumor (continued). "Interestingly, it has been reported that HMGB1 could directly increase the gene transcription and expression of P-gp in tumor cells." (PMID 26485677, 2015). "Thus, HMGB1 is a potent stimulator of sCLU production in DU145 tumor cells." (PMID 26469759, 2015). "The mechanism by which HMGB1 redox state is regulated in the tumor microenvironment remains unknown, and it is possible that these changes occur either prior to HMGB1 release from the dying cell or following the release of HMGB1 into the tumor microenvironment." (PMID 26486085, 2015). "HMGB1 is passively released from necrotic cells and actively secreted by inflammatory cells, and functions as an extracellular signaling molecule during processes such as inflammation, cell differentiation, tumor cell proliferation, cell migration and tumor metastasis." (PMID 25574225, 2015). "Furthermore, the amount of HMGB1 within the tumor microenvironment is positively correlated with the survival of esophageal squamous cancer patients, although the significance of HMGB1 is unclear; thus HMGB1 is a well-known and important molecule involved in RT-induced anti-tumor immunity." (PMID 25755254, 2015). "Thus, DTX-treated tumor cell supernatants contain HMGB1 that can induce sCLU." (PMID 26469759, 2015). "Therefore, the lower amount of HMGB1 in the serum of mice receiving ASA may be related to smaller tumor sizes." (PMID 26068794, 2015). "These high concentrations of HMGB1 over a relatively short period of time lead to effective activation of the acquired immune system, namely increased recruitment of dendritic cells (DC) that degrade engulfed apoptotic tumor cells, resulting in antigen presentation and specific T cell responses." (PMID 26854151, 2015). "Interestingly, different redox status of HMGB1 could have similar influence on tumour angiogenesis according to our results." (PMID 26099505, 2015). "Furthermore, HMGB1 could rapidly activate NFκB, a hallmark of TLR4/RAGE signaling, in DU145 tumor cells, as assessed by NFκBp65 phosphorylation." (PMID 26469759, 2015). "Likewise, in tumor patients an increased pathogenicity could be correlated to reduced serum levels of sRAGE as an indirect hint for a proportionately enhanced HMGB1 expression." (PMID 25525297, 2014). "However, because most studies have focused on the extracellular functions of HMGB1, its role, as an oncogene in tumor progression is largely unknown." (PMID 25051367, 2014). "In addition, HMGB1 promotes angiogenesis for tumor growth and metastasis; 4)." (PMID 25356587, 2014). "Real-time PCR analysis of HMGB1 mRNA expression revealed that the mRNA expression of HMGB1 was significantly upregul ated in BCa, and the mRNA expression in T2–T4 stage or high pathological grade tumor tissue was significantly higher than that in Ta-T1 stage or low pathological grade tumor tissue." (PMID 23426143, 2013). "Furthermore, HMGB1 plays a critical role in tumor immunology." (PMID 23866030, 2013). "However, cytoplasmic HMGB1 expression was exclusively observed in tumor cells." (PMID 22496788, 2012). "Moreover, anti-HMGB1 antibodies inhibited tumor angiogenesis." (PMID 23118492, 2012). "TLRs exist in almost immunosuppressive cells and recent study showed that tumor cell-derived HMGB1 might suppress naturally acquired CD8 T cell-dependent antitumor immunity via enhancing Treg to produce IL-10, which is necessary for Treg-mediated immune suppression." (PMID 22747650, 2012). "Consequently, a decreased interaction of tumor-derived HMGB1 with TLR4-expressing Treg might result in a decreased anti-tumor immune response in TLR4 Asp299Gly or Thr399Ile carriers which may result in a reduced DFS and OS." (PMID 21854645, 2011). "Following high-dose proton beam irradiation, tumor cells transfected with shRNA exhibited a significant reduction in CRT and HMGB1 expression compared with the con-shRNA-irradiated control group." (PMID 41641047, 2026).
tumor (continued). "The in vivo experiments revealed that plasma HMGB1 levels in the BNCT-treated mice were significantly elevated on the third day and remained highly expressed after tumor-volume reduction (Day 8)." (PMID 41328345, 2026). "The enhanced ATP, HMGB1, and CRT release, three typical DAMP signals, from cancer cells stimulated DCs maturation, facilitating more tumor infiltration by effective T cells." (PMID 41090529, 2026). "The impact of exosomal HMGB1 on macrophage plasticity was evaluated using THP-1-derived macrophage models, and therapeutic relevance was validated in murine tumour models under immunotherapy and chemotherapy regimens." (PMID 41645802, 2026). "Oncolytic viruses address this limitation by selectively replicating in tumor cells, inducing robust ICD characterized by four cardinal hallmarks: calreticulin exposure, ATP secretion, HMGB1 release, and type I interferon production." (PMID 42043250, 2026). "Our pH-sensitive nanozyme enables tumor-specificGOx delivery, initiating glucose depletion and ROS accumulation, whichin turn promote ICD through the release of DAMPs such as ATP, HMGB1,and calreticulin." (PMID 41493269, 2026). "Our findings delineate a previously unrecognised exosome-mediated mechanism by which HMGB1 drives NSCLC progression and modulates the tumour immune microenvironment." (PMID 41645802, 2026). "Tumor cells undergoing ICD effects, such as up-regulation of CRT and release of high-mobility group box 1 and ATP, act as auxiliary stimuli for DC maturation." (PMID 40110052, 2025). "Next, we measured expression of immunogenic proteins such as HMGB1, HSP70 and calreticulin in 1200V-treated apoptotic tumor cells by flow cytometry and demonstrated that they were all upregulated when compared to untreated or 600V-treated cells." (PMID 41194931, 2025). "Specifically, after infecting tumor cells, OBP-502 releases damage-related molecular patterns such as HMGB1 and adenosine triphosphate (ATP), which activate the immune system and promote antitumor immune responses." (PMID 41296391, 2025). "While serum HMGB1 concentrations in naïve C57Bl/6 and Balb/c were 7.65 ng/mL and 8.51 ng/mL, respectively, the concentrations in untreated B16F10 and 4T1 tumor-bearing mice were approximately a threefold increased, which further escalated over time." (PMID 40007542, 2025). "Upon infecting tumor cells, OV induce ICD, leading to the release of key danger signals such as high mobility group box 1 (HMGB1), adenosine triphosphate (ATP), and calreticulin (CRT)." (PMID 40977706, 2025). "These processes triggered the release/surface exposure of ICD‐related DAMPs, including CRT, HMGB1, ATP, and IFN‐β, leading to dendritic cells maturation and tumor immune microenvironment remodeling." (PMID 40504080, 2025). "The interplay between ferroptosis and cGAS-STING is pivotal: ferroptosis-driven ICD releases DAMPs (e.g., HMGB1, CRT), while Mn2+ amplifies cGAS-STING signaling to enhance type I interferon production, collectively inhibiting tumor growth and metastasis." (PMID 40846966, 2025). "Radiation‐induced HMGB1 release drives tumor cell dedifferentiation into a stem cell phenotype via the TLR2/YAP/HIF‐1α signaling pathway, thereby accelerating tumor recurrence and metastasis." (PMID 41354099, 2025). "The secreted HMGB1 can enhance the immune response to otherwise poorly immunogenic apoptotic cells by activating a TLR4-dependent, tumor-specific immune response." (PMID 41465435, 2025). "Subsequently, the cell swelling and membrane rupture induced the release of intracellular HMGB1, LDH, ATP, and other contents, which promotes tumor antigen presentation, maturation of DCs, T cell activation for anti-tumor immunity." (PMID 40698137, 2025). "Responders exhibited elevated expression of IL1B, CXCL5, HMGB1, and IFNGR2, indicative of an inflamed tumor microenvironment and type I/II interferon signaling." (PMID 40723289, 2025).
tumor (continued). "For instance, research has demonstrated that the mRNA and protein expression levels of HMGB1 are notably higher in bladder cancer (BUC) tissues and cell lines compared to non-tumor cells." (PMID 40877572, 2025). "Using granulosa-like tumor (KGN) cells, we investigated glycolytic capacity and examined the relationship among SNHG12, PTEN and HMGB1 through RNA immunoprecipitation (RIP) and chromatin immunoprecipitation (ChIP) assays." (PMID 40486908, 2025). "The reduced form of HMGB1 binds to the RAGE and induces Beclin-1-dependent autophagy, promoting tumor cell resistance to diverse chemotherapeutic agents including alkylators, tubulin disruptors, and DNA intercalators." (PMID 41465435, 2025). "Targeting HMGB1, combined with gemcitabine and ferroptosis inducer RSL3, can significantly inhibit tumor proliferation." (PMID 40495163, 2025). "ICD-inducing drugs enhance tumor antigen exposure and promote the release of immunostimulatory tumor cell content-related proteins, such as calreticulin (CRT), adenosine triphosphate (ATP), and high mobility group box 1 (HMGB1)." (PMID 40051630, 2025). "TIM-3 interacts with multiple ligands, such as Galectin-9, CEACAM1, phosphatidylserine (PtdSer), and HMGB1, promoting tumor immune tolerance and CD8+ T-cell exhaustion, thus facilitating tumor progression." (PMID 40552075, 2025). "In colorectal cancer, the HMGB1-RAGE axis promotes autophagy via ERK-mediated phosphorylation of Drp1, a mechanism contributing to both chemoresistance and tumor cell regeneratio." (PMID 40877572, 2025). "ANXA1 facilitates dendritic cell (DC) interactions with tumor debris by binding to formyl peptide receptor 1 (FPR1), while HMGB1 drives DC maturation by interacting with TLR4." (PMID 40004078, 2025). "Mechanistically, NE and HMGB1 released from NETs can bind to TLR-4 and TLR9, respectively, activating tumor cell proliferation, increasing mitochondrial biogenesis, and promoting the release of cytokines such as IL-6 and IL-8." (PMID 39849606, 2025). "Thus, we suspected that deficiency of KHSRP may suppress tumor progression and enhance the sensitivity of NSCLC cells to carboplatin by inhibiting EMT through downregulation of HMGB1 expression; whereas the precise underlying mechanisms require further investigation in future studies." (PMID 41194272, 2025). "Mechanistically, HMGB1 enhances angiogenesis by recruiting and activating macrophages, which subsequently stimulates secretion of VEGF, thereby facilitating tumor vascular formation." (PMID 41354099, 2025). "Pyroptosis is regulated by key molecules, including NOD‐like receptor family pyrin domain containing 3 (NLRP3), high mobility group box 1 (HMGB1), and caspase‐1, which are involved in inflammatory signaling and tumor microenvironment modulation." (PMID 41479846, 2025). "Mechanism I: Ferroptotic cells release DAMPs (HMGB1, ATP) that activate dendritic cells via TLR4/P2 × 7 receptors, triggering CCR7-dependent migration to lymph nodes where they prime tumor-specific T cells." (PMID 40887613, 2025). "It induces the release of ATP and HMGB1, leading to CD8+ T-cell infiltration and Foxp3+ T-cell suppression, thereby improving anti-tumor immunity." (PMID 40507337, 2025). "DAMPs such as CRT, HMGB1, and ATP, released or exposed during ICD, enhance APCs function, thereby amplifying anti-tumor immune responses." (PMID 40104638, 2025). "Immunohistochemical staining revealed concurrent overexpression of HMGB1, RAGE, Beclin-1, and LC3, indicating an activated autophagic pathway within tumor cells, while p62 expression was downregulated, reflecting autophagic flux." (PMID 41009692, 2025). "Functional experiments confirm that lactate in the hypoxic tumor microenvironment can induce GFAP-dedifferentiation in SCs, which promotes cancer cell invasion and progression through upregulating HMGB1." (PMID 40148311, 2025).
tumor (continued). "Through suppression of the HMGB1/TLR4 axis, AS-IV reduced M2 macrophage-mediated production of pro-tumor factors such as TGF-β, matrix metalloproteinase 9 (MMP-9), and IL-10." (PMID 40417220, 2025). "Radiation induces immunogenic cell death in tumor cells, leading to the release or exposure of DAMPs, such as calreticulin (CRT), dsDNA, ATP, and HMGB1." (PMID 40135850, 2025). "Following ICD, tumor cells release DAMPs, including calreticulin (CRT), high mobility group protein 1 (HMGB1), along with other factors such as adenosine‐5′‐triphosphate (ATP), and heat shock proteins (HSPs)." (PMID 40900811, 2025). "For instance, endogenous adjuvants, including ATP, CRT, and HMGB1, released by CpG-coated CpG PBNP promote the release of tumor antigens through PTT." (PMID 40688079, 2025). "This can activate TLR2 signaling in tumor cells, leading to the development of a chemotherapy-resistant phenotype, and it has previously been shown that TLR2 and HMGB1 have an important role in the self-renewal of breast CSCs." (PMID 40647457, 2025). "Radiation-induced HMGB1 release from dying cells activates Toll-like receptor 4 (TLR4)-dependent DCs, which in turn mediate a cytotoxic T-lymphocyte (CTL) response against tumor cells." (PMID 40598513, 2025). "Such dangers signals include the exposure of calreticulin (CALR) on the cell surface, the secretion of ATP, and the release of high mobility group box 1 (HMGB1), which collectively promote tumor-specific immune responses." (PMID 40635571, 2025). "It was verified that the Vpr peptide can induce ICD of tumor cells in vitro, as evidenced by the exposure of membrane-bound CRT, the release of HMGB1, and the release of ATP." (PMID 40733687, 2025). "HMGB1 and CRT are released from the nucleus into the cytoplasm, accompanied by significant morphological changes, highlighting the anti-tumor immunity mediated by pyroptosis." (PMID 40688079, 2025). "This demonstrates that HMGB1, by enhancing both DSB repair capacity, enables tumor cells to survive and evade the cytotoxic effects of anti-cancer therapies." (PMID 41465435, 2025). "In this context, emerging candidates such as GDF-15, VEGF, TGF-β1, HSP90, HMGB1, and S100A9 have garnered considerable attention for their roles in tumor progression, angiogenesis, immune modulation, and stress response." (PMID 41009692, 2025). "In HCC, HMGB1 released by tumor cells after chemoradiotherapy can be recognized by DC through TLR4, which induces DC maturation and anti-tumor immune responses." (PMID 40432108, 2025). "Fe2+/Fe3+ and DOX synergistically triggered tumor ferroptosis through LPO and GPX4 suppression, releasing DAMPs (e.g., mtDNA, HMGB1) to activate ICD." (PMID 40846966, 2025). "EVs are used by tumor cells as carriers for RNA, DNA, receptors, and proteins, including MMP2, MMP9, high mobility group box 1 (HMGB1), and CD147." (PMID 40345526, 2025). "HMGB1 binds to the RAGE signaling axis to accelerate ATP production, thereby providing energy to sustain the survival and proliferation of tumor cells." (PMID 41354099, 2025). "This protective signaling is often mediated by HMGB1’s interaction with its receptor, RAGE, leading to the activation of downstream survival pathways such as ERK1/2, which further promotes tumor cell proliferation and chemoresistance." (PMID 41465435, 2025). "To ensure reproducibility, we conducted additional in vivo experiments using an HMGB1-knockdown HCT116 model, the results of which were consistent with the SW480 data (tumor growth inhibition p < 0.01)." (PMID 40975711, 2025). "The results showed that the cell supernatants of the P1 and P4 treatment groups for MC38 and LLC cells had higher levels of HMGB1, indicating that P1 and P4 can promote the secretion of HMGB1 from MC38 and LLC tumor cells." (PMID 40733687, 2025). "In vivo experiments were performed using tumor-bearing mice treated with STAT3 and HMGB1 inhibitors." (PMID 40389855, 2025).